ENSG00000286235 (novel protein)
Gene: Protein-coding gene on chromosome 20 (5,950,949 to 6,039,856, forward strand). Ensembl gene ENSG00000286235.
Genetic constraint (gnomAD): Loss-of-function variants: 68 observed, 84.94 expected, observed/expected ratio (o/e) 0.8, 90% interval 0.66 to 0.98. Missense variants: 871 observed, 969.58 expected, observed/expected ratio (o/e) 0.9, 90% interval 0.85 to 0.95. Synonymous variants: 326 observed, 334.87 expected, observed/expected ratio (o/e) 0.97, 90% interval 0.89 to 1.07.